SEMA6A (semaphorin 6A)
Diseases named in the same sentence as SEMA6A in open-access papers (continued):
Sharing a sentence is not in itself a finding about the gene and the disease.
cancer (20 papers, 2018 to 2026). A tumor composed of atypical neoplastic, often pleomorphic cells that invade other tissues. "In most cancer types, upregulation of SEMA6A levels is associated with an overall poorer prognosis, increased invasiveness, and inhibition of apoptosis of mutated cells." (PMID 38067240, 2023). "First, it was attempted to analyze the differential expression level and prognostic risk of SEMA6A in pan-cancer from the Gene Expression Profiling Interactive Analysis (GEPIA) database." (PMID 37434634, 2023). "The role of SEMA6A in the development and progression of cancer has also been reported in recent years." (PMID 41259456, 2025). "SEMA6A is a multifunctional transmembrane semaphorin protein that participates in various cellular processes, including axon guidance, cell migration, and cancer progression." (PMID 36739418, 2023). "Using quantitative PCR, Prislei and colleagues have shown that beta-tubulin III (TUBB3) overexpression/silencing correlates with SEMA6A expression in ovarian A2780 cancer cells." (PMID 38067240, 2023). "SEMA6A is a transmembrane-binding protein that has been extensively studied in neurological disorders, but its role in malignant tumors has only recently been investigated." (PMID 37434634, 2023). "SEMA6A can form a complex with plexins to regulate the actin cytoskeleton, motility, and cell proliferation and is involved in cancer development." (PMID 36739418, 2023). "Collectively, SEMA6A is identified as a novel target gene of VHL-HIF-2α with a cancer-promoting role in ccRCC." (PMID 36739418, 2023). "In other words, these findings reveal SEMA6A as a new potential targetable protein to reverse drug resistance phenomena in cancer." (PMID 38067240, 2023). "Taken together, these results demonstrate that SEMA6A is a potential suppressor of cancer migration that functions through the NRF2/HMOX1 axis." (PMID 31527696, 2019). "In these studies, SEMA6A was identified as a factor that promotes cancer progression." (PMID 41259456, 2025). "Therefore, the Sema6a gene regulates processes related to different types of cancer, such as cell migration." (PMID 39596610, 2024). "Additionally, the semaphorins 5A and 6A (SEMA5A, SEMA6A) which we identified among the upregulated DEGs have been shown to act as the potential suppressors of cancer migration." (PMID 38383756, 2024). "Furthermore, we observed semaphorin 6A upregulated, and recent research profiled SEMA6A as a suppressor of cancer cell migration via the NRF2/HMOX1 axis." (PMID 37208732, 2023). "Recent research has also identified SEMA6A in cancer development." (PMID 37434634, 2023). "Finally, there is emerging evidence indicating that SEMA6A can drive the drug resistance of cancer cells through a remodeling of their cytoskeletons." (PMID 38067240, 2023). "However, the role of SEMA6A in cancer progression has been examined in only a few studies." (PMID 31527696, 2019). "Consequently, we posited that SEMA6A might play distinct roles in different cancers." (PMID 41259456, 2025). "Thus, we hypothesized that SEMA6A could suppress cancer cell migration." (PMID 31527696, 2019). "Thus, SEMA6A might represent a new potential therapeutic target in BRAFV600E cancers." (PMID 30374140, 2018). "For improving the understanding of SEMA6A-derived migration pathway, we also determined the mRNA expression levels of PLAU, MMP1 and MMP9 using RT-qPCR, because these genes were indicated to be reduced by HMOX1 and to induce migration in cancer cells." (PMID 31527696, 2019). "In addition, SEMA6A overexpression resulted in a marked decrease in liver metastasis of CRC cells, with decreased numbers of hepatic metastatic nodules and infiltration of cancer cells." (PMID 41259456, 2025).
psychiatric disorder (1 paper, 2011). A disorder characterized by behavioral and/or psychological abnormalities, often accompanied by physical symptoms. "We consider the phenotypes observed in Sema6A mutants in the context of what is known of the neuropathology, pathophysiology and pharmacology of psychiatric disorders, especially SZ and ASD." (PMID 22132072, 2011). "Convergent findings from physiological, behavioural and pharmacological experiments also suggest that the neurodevelopmental defects observed in Sema6A mutants result in endophenotypes that parallel some aspects of psychiatric disorders." (PMID 22132072, 2011).
SEMA6A also shares sentences with these, for which no sentence is quoted: glaucoma (2 papers); abscess (1); Alzheimer disease (1); asthenia (1); cardiovascular disease (1); Cerebral ischemia (1); exfoliation glaucoma (1); fibrosis (1); gastric cancer (1); Granuloma (1); granulomatosis with polyangiitis (1); leukemia (1); mental retardation (1); neovascular age-related macular degeneration (1); neurological disorders (1); papillary thyroid cancer (1); primary angle-closure glaucoma (1); systemic vasculitis (1).